STAT3 (signal transducer and activator of transcription 3)
Diseases named in the same sentence as STAT3 in open-access papers (continued):
Sharing a sentence is not in itself a finding about the gene and the disease.
tumor (continued). "Tumor cell-intrinsic STAT3 also modulates cytotoxic T-cell response by regulating expression of immune checkpoint molecules such as Programmed cell death 1 ligand 1 (PD-L1)." (PMID 32365499, 2020). "In tumour cells, folic acid activates the signal transducer and activator of transcription 3 (STAT3) pathway through FR-α." (PMID 32503320, 2020). "Various cytokines (e.g., IL-6, IL-10, and IL-11) that are released into the microenvironment by tumor cells have also been shown to activate STAT3." (PMID 32188095, 2020). "The phytoalexin RES has anti-inflammatory and chemopreventive effects, and it functions as a cyclooxygenase inhibitor; it can inhibit src tyrosine kinase and affect STAT3 activation in tumor cells." (PMID 32296578, 2020). "In PDAC, constitutive phosphorylation of STAT3 at Tyr705 has been reported in 30–100% of human tumor specimens." (PMID 32422890, 2020). "In turn, secreted IL-6 activates STAT3, which increases the level of expression of genes inducing tumor progression and metastasis." (PMID 32148497, 2020). "Studies have shown that the persistent activation of STAT3 is closely related to the malignant transformation of tumours." (PMID 32382281, 2020). "STAT5 signalling in tumour cells with active STAT3 reduced their proliferation and also sensitised the cells to treatment with paclitaxel and vinorelbine." (PMID 32872372, 2020). "Previous studies have shown that inhibiting JAK/STAT3 signalling in CSCs resulted in reduced tumour growth in vivo and interfered with CSC self-renewal." (PMID 32731620, 2020). "In GC, NF-κB and STAT3 act as oncogenes, enhancing the metastatic potential of tumor cells and contributing to the development and progression of the tumor." (PMID 33142817, 2020). "TESC induced by the TGFα/EGFR/signal transducer and activator of transcription 3 (STAT3) signaling pathway promotes cell proliferation and tumor growth in vivo and in vitro by increasing the expression of forkhead box M1 (FOXM1)." (PMID 32708604, 2020). "This is relevant, considering that activated STAT3 signaling in PDAC epithelium has been demonstrated to mediate tumor progression by promoting fibrosis and stromal stiffening." (PMID 32664564, 2020). "We show this by selecting the transcription factor activating kinase ERK1/2 and the transcription factor STAT3 as models for upstream regulation of HCC tumor cell growth." (PMID 32913557, 2020). "Compared to naïve IMCs, MDSCs from tumor-bearing mice demonstrate increased levels of STAT3 activation, and JAK2/STAT3 pathway plays an essential role in MDSC expansion from hematopoietic progenitor cells." (PMID 33335857, 2020). "The crosstalk between two transcription factors, Sp1 and STAT3, is essential for tumour angiogenesis and metastasis." (PMID 32144747, 2020). "Recipient mice that received cells from donors treated with STAT3 inhibitor displayed impaired tumor growth compared to both mice that receive lymphocytes from control tumor-bearing mice or non-reconstituted RAG1-/- mice." (PMID 33330068, 2020). "The reciprocal regulation of STAT3 and immune checkpoint molecules not only suggests an involvement of STAT3 in anti-tumor immunity, but also provides a promising strategy to improve the efficacy of current immune checkpoint inhibitors." (PMID 32972405, 2020). "The tumor immunohistochemistry data indicated more apoptosis and less proliferation activity in the STAT3-MB + UTMC treated tumors." (PMID 33206698, 2020). "In conclusion, miR-144-3p serves as a tumor suppressor in OSCC cells by directly targeting the ERO1L/STAT3 pathway." (PMID 31942199, 2020). "IL-6 present in the tumor microenvironment induces the M2 phenotype differentiation in macrophages through the activation of the STAT3 pathway." (PMID 32268527, 2020). "Constitutive activation of the signal transducer and activator of transcription 3 (STAT3) pathway is an important factor in determining the tumor stroma and hence considered as a potential target for cancer immunotherapy." (PMID 32823757, 2020).
tumor (continued). "OPB-51602 interferes with mitochondrial activity, and protein tumor cells expressing a mitochondrially restricted form of STAT3 are highly sensitive to OPB-51602, while STAT3-null cells are protected." (PMID 33158194, 2020). "Taken together, our study demonstrates that IL-17C promotes tumor angiogenesis through VEGF production via a STAT3/miR-23a-3p/SEMA6D axis, suggesting its potential as a novel target for anti-CRC therapy." (PMID 32492770, 2020). "The key inflammatory mediators for tumor proliferation and survival include NF-κB and signal transducer and activator of transcription 3 (STAT3)." (PMID 33143283, 2020). "NC inhibited cell viability via induction of apoptosis by hindering STAT3 pathway in oral cancer cell lines and a tumor xenograft model." (PMID 31956371, 2020). "used a mouse model showing that pre-existing STAT3 in myeloid cells that contribute to tumors such as MDSCs can considerably direct the TLR9 signaling process to the tumor angiogenesis and inhibition of antitumor immune responses." (PMID 33679700, 2020). "Activation of the JAK2/Signal transducer and activators of transcription 3 (STAT3) signaling pathwayhas revealed to have vital roles of tumorigenesis and progression in different human tumor cell types." (PMID 34675459, 2020). "In tumor cells, hyperactivated STAT3 promotes the expression of immunosuppressive factors such as VEGF, IL-6, and IL-10." (PMID 32972405, 2020). "Another colony-stimulating factor, tumor cell-secreted granulocyte–macrophage colony-stimulating factor (GM-CSF), has been shown to promote liver metastasis by inducing STAT3 phosphorylation in the liver MDSC." (PMID 33322216, 2020). "In light of those observations, we started investigating the result of the inhibition of STAT3 in a tumor experimental model." (PMID 33330068, 2020). "Activation of STAT3 is important for tumor-induced immunosuppression, which regulates the expression of immunosuppressive molecules." (PMID 32872659, 2020). "Constitutive activation of the TF signal transducer and activator of transcription 3 (STAT3) has been shown to be essential for the aggressiveness of the malignant tumours and thus making this TF as an attractive target for drug discovery." (PMID 36046384, 2020). "Aberrant STAT3 activation is related to cell malignant transformation, tumor proliferation, differentiation and anti-apoptosis." (PMID 32872659, 2020). "It has been observed that STAT3 phosphorylation is elevated in many human cancers and tumor-derived cell lines." (PMID 32425780, 2020). "Increasing evidence supports a potential role of STAT3 as a tumor driver in CTCL, and most human SS cells and CTCL cell lines display constitutively activate phosphorylated STAT3 (p-STAT3) with STAT3 inhibition resulting in massive apoptosis." (PMID 33333886, 2020). "Experimental studies on tumor-cell intrinsic STAT3 signaling mechanisms (particularly in the context of EGFR-driven NSCLC) further consolidated the notion of STAT3 as an oncogene in this disease." (PMID 32365499, 2020). "JAK-mediated STAT3 tyrosine phosphorylation compromises the antitumor immunity in tumor microenvironment and promotes the malignant cell proliferation and survival." (PMID 32005799, 2020). "STAT3 can also regulate angiogenesis in a variety of tumors and can also inhibit tumor invasion and metastasis." (PMID 33746736, 2020). "According to the authors, those anti-tumor activities were produced by a decrease in STAT3 and PD-1 levels." (PMID 33489912, 2020). "In tumor-forming rats, differential proteins were associated with tumor cell migration, TGF-β signaling and the STAT3 pathway." (PMID 32678190, 2020). "MiR-155 is also related inflammation since IL-6 induces its expression and this in turn activates the JAK2/STAT3 pathway, thus promoting tumor inflammation." (PMID 33059744, 2020).
tumor (continued). "A growing body of evidence suggests that the signal transducer and activator of transcription 3 (STAT3) pathway is involved in multiple signaling pathways related to tumor progression and evasion of the immune system." (PMID 33173024, 2020). "Transfer of B cells expressing STAT3 to Rag1−/− mice leads to enhanced tumor growth accompanied with increased angiogenesis." (PMID 31690961, 2020). "Activated STAT3 is a critical contributor of cancer cell survival and proliferation, and tumor invasion, metastasis." (PMID 33335857, 2020). "As a proinflammatory mediator, IL-6 binds to gp130 in the tumor microenvironment, resulting in the phosphorylation of STAT3 after JAK activation." (PMID 33082817, 2020). "The fourth, most common neoplasm of this organ—pancreatic ductal carcinoma (PDAC)—is characterized by constitutive activation of STAT3 with a 5-year survival rate <5%." (PMID 33158194, 2020). "In many human cancers, an abnormally hyperactivated IL-6/STAT3 signaling has been observed in tumor cells and cells of the tumor microenvironment, and pro-tumorigenic characteristics of both, IL-6 and STAT3, have been described." (PMID 33257655, 2020). "FKBPL-based therapy can (i) dually target angiogenesis and CSCs, (ii) target the CD44/STAT3 pathway in tumours and (iii) is effective in highly vascularised HGSOC tumours with low levels of IL-6." (PMID 31772325, 2020). "STAT3 signaling in myeloid cells can be initiated by tumor derived factors, including IL-10 and lactate." (PMID 32983100, 2020). "Signal Transducer and Activator of Transcription 3 (STAT3) mediates the intracellular signaling of tumor-associated immunosuppressive cytokines, such as interleukin (IL)-10; thus, we hypothesized that STAT3 restrained anti-tumor immune responses elicited by CD103+ cDC1s." (PMID 31947933, 2020). "Further studies identified that PLXNC1 promoted GC proliferation in vitro and in vivo, as well as migration in vitro by activating tumor-related pathways such as the IL-6/STAT3 signaling pathway." (PMID 32117710, 2020). "Stat3, an intracellular transducer of immune-related signaling, acts to promote proliferation, angiogenesis, metastasis, and immune escape in tumor cells." (PMID 32707672, 2020). "In murine xenograft tumor models, lipoxin A4 is able to suppress tumor growth by targeting immune-suppressive IL-10-producing regulatory B cells via dephosphorylation of STAT-3 and extracellular signal-regulated kinase." (PMID 32676076, 2020). "STAT3 signaling contributes to crosstalk between tumor and immune cells, including macrophages, CD8+ T-cells, myeloid-derived suppressor cells, and regulatory T-cells." (PMID 33096674, 2020). "STAT3 inhibition resulted in increased anti-tumor activity and superior responses to immunotherapy and immunogenic chemotherapy in several pre-clinical studies and trials." (PMID 32630675, 2020). "IL6 mediated the cross talk between normal fibroblasts and the cancer cells, and promoted tumor cell migration through the STAT3 pathway." (PMID 31636361, 2020). "Studies have shown that STAT3 can regulate the genes that inhibit the apoptotic pathway and ultimately contribute to the development of tumours." (PMID 32869923, 2020). "At the molecular level, loss of PTEN in tumor cells leads to a significant downregulation of SHP‐2 (Src homology‐2‐containing protein tyrosine phosphatase 2), a negative regulator of the JAK/STAT3 pathway." (PMID 32875727, 2020). "IL-6, a major mediator of inflammation, induces the expression of STAT3 target genes and drives tumor growth and/or survival." (PMID 32883032, 2020). "STAT-3 is a downstream signal transducer of cytokine signaling and is positively correlated with tumor angiogenesis." (PMID 33511267, 2020). "As STAT3 signaling is activated in cancer, it is possible that although the sections were distant from the tumor and defined ‘normal’ by histology, several molecular pathways were still activated." (PMID 32070329, 2020).
tumor (continued). "Overall, the outcome of STAT3-mediated crosstalk between cancer cells and tumor-infiltrating cells within the TME is to promote tumor growth and development, along with diminished anti-tumor immunity." (PMID 32972405, 2020). "As a single agent, Benz was able to reduce the levels of the p-STAT3, uSTAT3, and NF-κB, factors essential for cancer cell survival and tumor progression." (PMID 32102440, 2020). "Stat3 is a well-established molecule in JAK/Stat3 signaling pathway to initiate and promotes tumor progression." (PMID 32754442, 2020). "One study demonstrated that the IL-6/JAK/STAT3 pathway plays an important role in the tumor microenvironment and drug research." (PMID 32792945, 2020). "Immunohistochemical assays showed decreased intensity of Ki67, p‐STAT3 (Tyr705), and cleaved caspase‐3 staining in tumours from mice treated with HJC0152." (PMID 32022328, 2020). "Interrupting the interaction between CPAP and STAT3 attenuates STAT3-mediated tumor growth and angiogenesis." (PMID 31511651, 2020). "Tumour associated neutrophils (TANs) induce EMT in gastric epithelium by the release of IL-17a and activation of IL-17a/JAK2/STAT3 signaling (pathway 6)." (PMID 32899442, 2020). "Activated STAT3 regulates a variety of tumor cell processes, such as tumor cell growth, survival, invasion, cancer stemness, and chemoresistance, and has been shown to contribute to disease aggressiveness in ovarian cancer." (PMID 33424607, 2020). "IGF-2, which is present in tumor cells, can be secreted by activated STAT3 to impair the antitumor efficacy of anti-IGF-2 therapy." (PMID 32398034, 2020). "Constitutively active STAT3 promotes the enhancement of aerobic glycolysis and proliferation, as demonstrated by the inhibition of STAT3 in an experimental tumor xenograft model that triggered a decreased glucose uptake." (PMID 33003453, 2020). "In this review, we will define the signal transducer and activator of transcription 3 (STAT3) protein’s role in the tumor formation process and summarize the role of STAT3 in skeletal muscle cachexia." (PMID 33158194, 2020). "The protein levels of p-STAT3 protein were significantly lower in tumor tissues from the NaB group than the control group." (PMID 32518521, 2020). "TNFRSF1A mediates STAT3 phosphorylation and promotes the accumulation of myeloid suppressor cells in the tumor microenvironment." (PMID 33028341, 2020). "Tumor cell-derived EVs have been reported to induce high expression of PD-L1 via STAT3 pathway in macrophages and monocytes, representing an immunosuppressive M2 phenotype." (PMID 32477934, 2020). "Aberrantly activated STAT3 can lead to tumor-induced immunosuppression via propagating the crosstalk between cancer cells and their immunological microenvironment." (PMID 32972405, 2020). "As an acute phase protein, the activation of STAT3 is transient under normal conditions, but in tumor cells, there is a constitutive activation." (PMID 32850390, 2020). "On the other hand, corosolic acid inhibits the M2 polarization of macrophages and tumor cell proliferation by inhibiting both STAT3 and NF-κB activation." (PMID 32640667, 2020). "We also previously revealed that natural compound-derived STAT3 inhibitors, such as corosolic acid and onionin A, enhanced the efficacy of chemotherapeutic agents against tumor cells." (PMID 32256354, 2020). "One study established a positive feedback signaling loop formed by TGF-β and IL-6/JAK2/STAT3 signaling pathways, which mediates interactions between MF and tumor cells." (PMID 33262947, 2020). "By contrast, STAT3 signaling in moDCs inhibited expression of the transcriptional regulator Id2, a pathway that suppressed moDC-mediated anti-tumor activity." (PMID 31947933, 2020). "The expression of PD-L1 on tumor MDSCs was modulated by the miR-93/106b miRNA cluster of miR-17 family through the STAT3 pathway." (PMID 33613512, 2020).
tumor (continued). "STAT3 has also been confirmed as a critical molecular driver for FoxP3 expression and Treg immunosuppressive phenotype in the tumor setting." (PMID 33335857, 2020). "Several studies identified STAT3 as an important interaction partner for CD44 in promoting tumor properties across various cancer models, including ovarian." (PMID 33335857, 2020). "More importantly, STAT3 activation also results in the production of factors that benefit tumor viability and invasiveness, such as VEGF, matrix metalloproteases, and IDO." (PMID 32983100, 2020). "miR-125b inhibits the tumor growth and progression in two ways: (i) by influencing the STAT3 pathway, and (ii) by negatively regulating the downstream targets Cyclin D1 and Bcl2, involved in the cell cycle and apoptosis processes, respectively." (PMID 32911687, 2020). "For example, the protein encoded by the proto-oncogene c-Myc is a downstream target of STAT3 that is thought to be involved in tumor initiation and development." (PMID 31949488, 2020). "STAT3 is involved in angiogenesis and tumor progression through polarization of TAMs to the M2 phenotype." (PMID 32486098, 2020). "Pull-down experiments with an activity-based probe (ABP) of SFN in HBCx34 PDX tumor cells confirmed direct interaction of SFN with STAT3 in both antiestrogen and vehicle-treated tumors, establishing STAT3 as the likely target of SFX-01." (PMID 32472077, 2020). "It has also been reported that the IL-6/STAT3 pathway plays an essential role in tumor progression in CRC23,24." (PMID 32358527, 2020). "As a multi-targeted tyrosine kinase inhibitor, sunitinib also inhibits STAT3 in tumor cells such as renal and medulloblastoma tumor cells." (PMID 32927828, 2020). "But, in cancer, TGF-β/SMAD signaling promotes the secretion of IL-11 by CAFs, which triggers GP130/STAT3 signaling in tumor cells, increasing the efficiency of tumor metastasis formation." (PMID 33322749, 2020). "On the contrary, tumor suppressive properties of STAT3 have also been reported through the regulation of targets such as FOXP337." (PMID 32352029, 2020). "Briefly, the down-regulation of lincRNA-p21 reduces its interaction with STAT3, and consequently activates the transcriptional activity of STAT3 and promotes tumor progression." (PMID 32582435, 2020). "Meanwhile, immunohistochemistry analysis further confirmed that after being exposed to Cc/Glt NM, the expression of Bip in the tumor was upregulated, verifying that ER stress was activated, which further reduced phosphorylation of STAT3 in tumors." (PMID 32891174, 2020). "Considering the correlation between STAT3 and tumor purity, STAT3 and abundance of TIICs, we focused on BLCA, KICH, and PRAD to study the correlation between STAT3 and immune cells." (PMID 32486001, 2020). "This is also the case in cancer, where signal transducer and activation of transcription 3 (STAT3) is a great potential therapeutic candidate that has been targeted using a small-molecule degrader for complete tumor regression." (PMID 32373125, 2020). "To further characterize targets of Trichomicin in the tumor microenvironment, we investigated the effects of Trichomicin on the Stat3 and NF-κB pathways in CAFs stimulated with CRC supernatants." (PMID 32317968, 2020). "STAT3 signalling, across several cell types in the tumour microenvironment, plays a major role in tumour development and progression." (PMID 32731620, 2020). "Several studies have shown that the activation of STAT3 contributes to tumor development including bone, breast, prostate, skin, ovary, blood, and lung 27-29." (PMID 31929760, 2020). "Among these, STAT3 is a transcription factor that is involved in tumor development and progression as well as inflammation." (PMID 33053804, 2020). "Signal Transducers and Activators of Transcription 3 (STAT3) is reported to be upregulated in many tumor types, and it is believed to be involved in the tumorigenesis, development and malignant behaviors of tumors." (PMID 32733808, 2020).